AMH (anti-Mullerian hormone)
Diseases named in the same sentence as AMH in open-access papers (continued):
Sharing a sentence is not in itself a finding about the gene and the disease.
vitamin D deficiency (13 papers, 2018 to 2025). A nutritional condition produced by a deficiency of VITAMIN D in the diet, insufficient production of vitamin D in the skin, inadequate absorption of vitamin D from the diet, or abnormal conversion of vitamin D to its bioactive metabolites. "In contrast, a prospective study involving PCOS women found an association between vitamin D deficiency and decreased serum AMH levels." (PMID 34154571, 2021). "The results of our single arm uncontrolled study showed that the serum level of vitamin D in patients with vitamin D deficiency increased significantly after the intervention and consequently their serum AMH increased significantly after the intervention." (PMID 34154571, 2021). "The last evidence was conducted among infertile and fertile females (18–40 years old) to investigate the correlation of vitamin D deficiency with serum AMH." (PMID 34362981, 2021). "Serum levels of AMH were compared between 1561 women with vitamin D insufficiency/deficiency and 924 women with sufficient vitamin D status using 8 studies yielded non-significant difference (WMD 0.02 ng/mL; 95% CI − 0.40 to 0.43; P = 0.929) with evidence of heterogeneity (I2 = 63.2%, P = 0.008)." (PMID 34362981, 2021). "Also, Cappy and coworkers were unable to demonstrate any significant correlation between vitamin D supplementation and AMH levels in women with PCOS diagnosed with vitamin D deficiency." (PMID 31089932, 2019). "Similarly, Merhi and coworkers observed a positive correlation between serum concentrations of vitamin D and AMH, thus suggesting a relationship between low ovarian reserve and vitamin D deficiency." (PMID 31089932, 2019). "Additionally, the group of included patients was rather homogeneous: European descent mainly living in Germany; no participant was dark-skinned, as women with dark skin tone seem to have more likely a vitamin D deficiency, tend to have lower serum AMH levels and an earlier onset of menopause." (PMID 35220479, 2022). "When anti‐Müllerian hormone (AMH) and vitamin D were measured in premenopausal women, a positive correlation was found between AMH and vitamin D concentration among those aged ≥ 40 years, and the data have shown a correlation between vitamin D deficiency and decreased AMH." (PMID 32684824, 2020). "Vitamin D is involved in the regulation of AMH and FSH gene expression, and high dose 25(OH)D3 has been shown to increase serum AMH levels in vitamin D insufficiency." (PMID 30761082, 2019). "According to the literature, abnormal anti-Müllerian hormone (AMH) levels and significant vitamin D deficiency are responsible for a number of different abnormalities observed in PCOS patients." (PMID 31089932, 2019). "When AMH values are employed in clinical assessment, vitamin D insufficiency must be considered." (PMID 37701195, 2023). "Even though investigations have exposed that environmental variables like vitamin D insufficiency could change AMH expression and blood concentrations, AMH is still one of the strongest screening indicators for ovarian reserve." (PMID 37701195, 2023). "Several hormonal factors are responsible for promoting such risk factors, including high levels of gonadotropin-releasing hormone (GnRH), follicle-stimulating hormone (FSH), luteinizing hormone (LH), insulin, androgen, anti-Müllerian hormone (AMH), vitamin D deficiency, and calcitonin." (PMID 35643521, 2022).
Anxiety (12 papers, 2021 to 2025). Intense feelings of nervousness, tension, or panic often arise in response to interpersonal stresses. "Data regarding the association of specific psychiatric conditions such as anxiety and depression with lower AMH levels has been conflicting." (PMID 41196903, 2025). "As anti-Müllerian hormone (AMH) is the most established marker for ovarian reserve, we chose AMH as a further potential risk factor for SD/depression/anxiety." (PMID 38381389, 2024). "Furthermore, we have found marked reductions in serum AMH levels in female firefighters associated with self-reported clinical diagnoses of anxiety and posttraumatic stress disorder, as well as characterizations of stress and posttraumatic stress disorder." (PMID 40262139, 2025). "Lifestyle factors (e.g., diet, exercise) and pre-existing psychological conditions (e.g., anxiety or depression) can also serve as confounding variables to AMH level fluctuations." (PMID 41196903, 2025). "Meanwhile, it is important to avoid unnecessary fertility anxiety among reproductive-aged females, especially young nulliparas with decreased serum AMH levels." (PMID 34721287, 2021). "Low serum levels of AMH have also been connected to psychological stress and anxiety intensity." (PMID 38738039, 2024). "Additionally, low plasma AMH measures were also related to emotional stress and the severity of anxiety." (PMID 38738039, 2024). "It has also been shown that stress and anxiety play a role in lowering AMH levels." (PMID 39906086, 2024). "The current spread of AMH testing may generate anxiety and undue stress, as well as over-treatment." (PMID 39340554, 2024). "Day 3 hormonal analysis results for the female partner (including AMH, FSH, LH, estradiol (E2) and prolactin (PRL) levels) were similar between groups except the mean FSH level that was significantly elevated in case of moderate anxiety in comparison with severely anxious patients." (PMID 35233270, 2021). "↓ HbA1C, ovary mass, stress, anxiety and depression (HADS),↔ weight, Prolactin, FSH, LH, AMH, TT,No adverse events occurred." (PMID 38818503, 2024).
Hyperinsulinemia (12 papers, 2015 to 2026). An increased concentration of insulin in the blood. "Higher body mass index, hyperinsulinemia, elevated triglycerides (TGs), and reduced anti-Müllerian hormone (AMH) levels were independently associated with an increased risk of OSA in women with PCOS." (PMID 42063789, 2026). "Metformin enhances insulin sensitivity by lowering blood glucose levels and decreasing hyperinsulinemia, which indirectly affects AMH levels." (PMID 40281834, 2025). "Another cause for the increase in AMH and androgens in PCOS is secondary to hyperinsulinemia, because it enhances gonadotropin-stimulated steroid production in granulosa and theca cells." (PMID 28913122, 2016). "Metformin, by improving insulin sensitivity and reducing hyperinsulinemia, may have an indirect effect on AMH levels." (PMID 40281834, 2025). "Conversely, a higher number of follicles reflected by high AMH levels could determine higher androgen levels related to hyperinsulinemia." (PMID 31735163, 2019). "The distinct effect of myoinositol on testosterone, AMH, and ovarian volume is surprising and this could be explained by a reduction in hyperinsulinism." (PMID 27882049, 2016). "Inwomen suffering from PCOS hyperinsulinemia mayincrease AMH levels." (PMID 32112632, 2020).
hypogonadotropic hypogonadism (12 papers, 2016 to 2026). Abnormal ovarian or testicular function due to insufficient hormonal stimulation from the hypothalamic-pituitary axis. "Our case series present rare cases of increased AMH in patients with PCOS and other conditions, emphasizing the important role of AMH as a diagnostic marker in women with hypogonadotropic hypogonadism and granulosa cell tumors." (PMID 41515619, 2026). "In boys with congenital central hypogonadism, low inhibin B and AMH levels indicate a Sertoli cell hypoplasia secondary to pituitary gonadotropin deficiency reflecting a long-term insufficient FSH activity on Sertoli cell proliferation and function." (PMID 37260445, 2023). "This explains why serum AMH levels are low, in coincidence with small testicular size, in boys with congenital central (hypogonadotrophic) hypogonadism and increase after FSH treatment." (PMID 35712256, 2022). "AMH dosage can also prove useful in differential diagnosis between constitutional delay of growth and congenital hypogonadotropic hypogonadism, but little uses are known so far for AMH in adult life." (PMID 32026338, 2020). "Insufficient AMH signaling to GnRH neurons interferes with their development and results in hypogonadotropic hypogonadism." (PMID 33551743, 2020). "Conversely, in patients with central hypogonadism treated with exogenous testosterone, serum AMH remains high indicating that intratesticular androgen concentration is low." (PMID 27799946, 2016). "In normally virilized boys, low serum AMH is seen in patients with primary or central hypogonadism." (PMID 35712256, 2022). "Serum AMH is below the normal range in most cases of isolated central hypogonadism and of multiple pituitary hormone deficiency, although normal AMH levels do not rule out the diagnosis." (PMID 27799946, 2016). "However, Cedars emphasizes that AMH must be interpreted in the context of the overall endocrine environment, as conditions such as hypogonadotropic hypogonadism or the use of hormonal contraceptives can lower AMH levels without accurately representing ovarian reserve." (PMID 39683543, 2024). "Serum AMH is also a reliable marker of FSH action in the prepubertal testis, both in basal conditions to diagnose central hypogonadism and to monitor FSH treatment." (PMID 27799946, 2016). "However, in men with central hypogonadism, FSH stimulation results in an increase in AMH levels." (PMID 36769720, 2023).
granulosa cell tumor (11 papers, 2010 to 2026). A slow-growing, malignant tumor, characterize by the presence of granulosa-like cells and Call-Exner bodies, that is almost always found in the ovary. "6.AMH is a specific circulating indicator of granulosa cell tumors, with a diagnostic sensitivity of 76–91% and specificity of 90–100%." (PMID 40597965, 2025). "In young patients, BGCS and ESGO recommend an extended panel including AFP, β-hCG, LDH, Inhibin B, and AMH to detect germ cell or granulosa cell tumors." (PMID 41463165, 2025). "Serial measurement of serum AMH in granulosa cell tumor patients is performed in order to assess the efficacy of surgical treatment and to monitor possible relapses of the disease." (PMID 30884769, 2019). "Since the granulosa cell tumors secrete AMH in proportion to tumor burden, the changes in serum AMH reflect both recurrences and response to therapy." (PMID 30884769, 2019). "The fact that AMH expression is restricted to ovarian granulosa cells in women led to establishing AMH levels as a serum marker of granulosa cell tumours (GTCs)." (PMID 23983687, 2013). "We analyzed the expression of inhibin-α and anti-Müllerian hormone (AMH, also known as Müllerian Inhibiting Substance), which are the two markers most often used to detect murine, human, and equine granulosa cell tumors, in Amhr2-Cre;Ctnnb1Δ(ex3)/+ tumors." (PMID 21695255, 2011). "Determination of serum AMH is used in diagnosing granulosa cell tumors." (PMID 30884769, 2019). "Additionally, increased AMH in rare cases might suggest granulosa cell hyperplasia (GCH) or granulosa cell tumors (GCTs), but the elevated AMH values often overlap in patients with PCOS and GCTs." (PMID 41515619, 2026). "The difficulties in the differential diagnosis of patients with elevated AMH levels, because of PCOS combined with pituitary dysfunction, increased ovarian volume, or granulosa cell tumors (GCTs), are discussed." (PMID 41515619, 2026). "Thus, the increased AMH levels resulting from increased AMH secretion in the granulosa cells, an increased number of granulosa cells (“mass effect”), or granulosa cell tumors with moderate AMH secretion might affect the gonadotropin ratio and steroidogenesis, leading to similar clinical symptoms." (PMID 41515619, 2026). "Anti-mullerian hormone (AMH) is a well-known marker for normal granulosa cells and granulosa cell tumors." (PMID 24603706, 2014). "However, we showed that these tumors failed to express markers of granulosa cell tumors (AMH and inhibin-α), and express epithelial markers suggesting an epithelial origin for these tumors." (PMID 21695255, 2011).
male infertility (11 papers, 2013 to 2025). The inability of the male to effect fertilization of an ovum after a specified period of unprotected intercourse. "In our present study, we found that the phenotypes in Ppp6ccKO mice are similar to those of previously reported conditional activated allele of the β-catenin in Sertoli cells by using AMH-Cre or Amhr2-Cre by transgenic mouse, including male infertility and the loss of germ cells." (PMID 34580275, 2021). "The FITMI study is therefore highly relevant and is the first RCT designed to evaluate the effectiveness of denosumab as a first-in-class treatment for male infertility in men with impaired semen quality and high serum AMH." (PMID 35733213, 2022). "Ovarian reserve tests such as serum AMH levels have been shown to be of limited value in predicting IVF outcomes in the presence of unexplained or male infertility, prompting the need to take male factors into account when predicting IVF outcomes using AMH." (PMID 31393936, 2019). "Age, AMH values, body mass index, ratio of cycles with combined male infertility, and estradiol values were comparable." (PMID 28097133, 2016). "However, due to the limitation of sample size and inclusion of couples with male infertility, we cannot debate on wider role of AMH in predicting pregnancy outcomes." (PMID 27648045, 2016). "Thus, the clinical applications of AMH measurement in predicting quantitative and qualitative aspects of male infertility remain controversial." (PMID 24098470, 2013). "In recent years, research hotspots have focused on AMH INHB, DFI, acrosome reaction, mitochondrial membrane potential, sperm membranes, neutral α‐glucosidase and fructose concentrations, which may become a key reference circle for the diagnosis and treatment of male infertility." (PMID 34270116, 2021).
ovarian endometriosis (11 papers, 2015 to 2025). A non-neoplastic disorder characterized by the growth of endometrial tissue in the ovaries. "Previous reports have demonstrated that diminished ovarian reserves resulted in decreased anti-Müllerian hormone (AMH) levels in patients with ovarian endometriosis." (PMID 40648868, 2025). "The faster decrease of the AMH residual levels with age was further confirmed when either considering all ovarian endometriosis cases (n = 155), or separating bilateral (n = 35) from unilateral (n = 120) cases (data not shown)." (PMID 28791295, 2017). "Serum AMH levels were significantly lower in women with bilateral ovarian endometriosis who were under 43 years of age than in age-matched patients with unilateral endometriomas and healthy individuals." (PMID 26596960, 2015). "Therefore, it is necessary to detect AMH level in time to evaluate the severity of ovarian endometriosis and the possibility of successful pregnancy after operation." (PMID 37560165, 2023). "AMH levels in peritoneal fluids may differ according to the presence of ovarian endometriosis which lowers productions of AMH from ovarian granulosa cells." (PMID 33263001, 2020). "Patients with bilateral ovarian endometriomas showed the lowest median AMH levels compared with patients suffering from unilateral ovarian endometriosis (0.55; IQR: 0.59 vs. 2.00; IQR: 2.80; p < 0.001) and the control group (0.55; IQR: 0.59 vs. 2.84; IQR: 3.2; p < 0.001)." (PMID 26596960, 2015). "Moreover, patients under 43 years of age with bilateral ovarian endometriosis showed significantly lower serum AMH concentration compared to patients with unilateral ovarian endometriosis and healthy controls." (PMID 26596960, 2015). "Patients with bilateral ovarian endometriomas presented the lowest median AMH levels, compared to women suffering from unilateral ovarian endometriosis (0.55; IQR: 0.59 vs. 2.00; IQR: 2.80; p < 0,001) and the control group (0.55; IQR: 0.59 vs. 2.84; IQR: 3.2; p < 0.001)." (PMID 26596960, 2015). "To clear this hypothesis, we set up a prospective study evaluating AMH levels in women with ovarian endometriosis." (PMID 26596960, 2015). "Moreover, in patients undergoing laparoscopic cystectomy due to ovarian endometriosis, a significant reduction in AMH secretion was reported." (PMID 26596960, 2015). "Diminished anti-Mullerian hormone (AMH), low antral follicle counts, and lower response to ovarian stimulation, may caused by ovarian endometriosis regardless of surgery." (PMID 35145654, 2022). "However, the main question remains whether fertility preservation should be recommended to every woman with ovarian endometriosis considering surgery and planning for a future pregnancy and whether preoperative serum AMH levels are essential for adopting this strategy." (PMID 36213292, 2022). "In women with bilateral ovarian endometriosis, a moderately negative correlation between AMH levels and age was observed (R = −0.663; p < 0.001)." (PMID 26596960, 2015). "In the present study, we showed a significantly negative correlation between serum AMH concentration and age in women with bilateral and unilateral ovarian endometriosis." (PMID 26596960, 2015). "Median AMH concentration values were not significantly different between patients with unilateral ovarian endometriosis and the healthy controls (2.00; IQR: 2.80 vs. 2.84; IQR: 3.2; p = 0.182)." (PMID 26596960, 2015). "Patients with unilateral ovarian endometriosis showed a significantly negative correlation between serum AMH level and age." (PMID 26596960, 2015). "According to our data, unilateral ovarian endometriosis had a moderately negative and nonsignificant effect on AMH-based ovarian reserve evaluated prior to surgery, irrespective of age." (PMID 26596960, 2015). "A strong negative correlation between AMH levels and age was confirmed in the healthy controls (R = −0.834; p < 0.001) and women with unilateral ovarian endometriosis (R = −0.774; p < 0.001)." (PMID 26596960, 2015).
ovarian endometriosis (continued). "According to our data, unilateral ovarian endometriosis moderately impaired AMH-based ovarian reserve prior to surgery, irrespective of age." (PMID 26596960, 2015). "However, patients with bilateral ovarian endometriomas showed a significantly weaker correlation between AMH levels and age compared to the controls (R = −0.633 vs. R = −0.834; p = 0.006) but not the patients with unilateral ovarian endometriosis (R = −0.663 vs. R = −0.774; p = 0.093)." (PMID 26596960, 2015). "Importantly, further research is needed to elucidate the role of AMH in guiding fertility counseling and treatment planning, especially in non-OMA phenotypes and extra-ovarian endometriosis." (PMID 40507534, 2025).